PEX13 (peroxisomal biogenesis factor 13)
Description:
Component of the PEX13-PEX14 docking complex, a translocon channel that specifically mediates the import of peroxisomal cargo proteins bound to PEX5 receptor. The PEX13-PEX14 docking complex forms a large import pore which can be opened to a diameter of about 9 nm (By similarity). Mechanistically, PEX5 receptor along with cargo proteins associates with the PEX14 subunit of the PEX13-PEX14 docking complex in the cytosol, leading to the insertion of the receptor into the organelle membrane with the concomitant translocation of the cargo into the peroxisome matrix. Involved in the import of PTS1- and PTS2-type containing proteins.
Synonyms: NALD; PBD11A; PBD11B; ZWS
Tractability: Antibody: UniProt predicts a signal peptide or a membrane-spanning region. PROTAC: ubiquitination databases record sites on it; its protein half-life has been measured.
Gene: Protein-coding gene on chromosome 2 (61,017,225 to 61,051,990, forward strand). Ensembl gene ENSG00000162928.
Subcellular location: Peroxisome membrane
Subcellular location (Human Protein Atlas): Peroxisomes
Pathways (Reactome):
Protein localization: Class I peroxisomal membrane protein import; Peroxisomal protein import
Metabolism of proteins: E3 ubiquitin ligases ubiquitinate target proteins
Gene Ontology:
Molecular function: protein binding; protein transmembrane transporter activity
Biological process: cellular response to reactive oxygen species; protein import into peroxisome matrix, docking; protein import into peroxisome matrix, translocation; cerebral cortex cell migration; fatty acid alpha-oxidation; locomotory behavior; microtubule-based peroxisome localization; neuron migration; suckling behavior
Cellular component: membrane; peroxisomal importomer complex; peroxisomal membrane; peroxisome; cytosol
Genetic constraint (gnomAD): Loss-of-function variants: 23 observed, 28.12 expected, observed/expected ratio (o/e) 0.82, 90% interval 0.59 to 1.16. The upper end of that interval is the gene's LOEUF score, 1.16, which puts it in group 5 of 6, group 1 being the genes least tolerant of losing a copy. Missense variants: 493 observed, 449.3 expected, observed/expected ratio (o/e) 1.1, 90% interval 1.02 to 1.18. Synonymous variants: 164 observed, 162.12 expected, observed/expected ratio (o/e) 1.01, 90% interval 0.89 to 1.15.
Gene-disease validity (ClinGen):
ClinGen rates the evidence that PEX13 causes each of these diseases.
peroxisome biogenesis disorder (autosomal recessive): Definitive.
Homologues: Orthologues: chimpanzee PEX13 (100% identical), macaque PEX13 (99% identical), dog PEX13 (95% identical), rabbit PEX13 (94% identical), guinea pig PEX13 (93% identical), rat Pex13 (92% identical), mouse Pex13 (91% identical), tropical clawed frog pex13 (70% identical), zebrafish pex13 (63% identical), Caenorhabditis elegans prx-13 (31% identical), Drosophila melanogaster Pex13 (28% identical).
Diseases named in the same sentence as PEX13 in open-access papers:
PEX13 is named in the same sentence as 17 diseases in open-access papers, as found by Europe PMC text mining. Sharing a sentence is not in itself a finding about the gene and the disease. The quoted sentences say what the papers report.
Zellweger syndrome (9 papers, 2016 to 2025). "It has been demonstrated that impaired mitophagy induced by mutations in the PEX13 protein is the cause of Zellweger syndrome, which is detrimental to the health of newborns." (PMID 40002740, 2025). "We report six patients affected by Zellweger spectrum disorder, ranging from moderate to severe clinical phenotype, carrying either truncating or missense variants in the PEX13 gene." (PMID 35854306, 2022). "Mutations in PEX13, lead to Zellweger syndrome (ZS), associated with impaired neuronal migration, neuronal positioning, and brain development." (PMID 32377374, 2020). "The phenotype of mice with Pex2, Pex5 and Pex13 deficiency resembles the severe form of human Zellweger syndrome." (PMID 26686055, 2016). "Genetic deletion of Pex2, Pex5, or Pex13 in mice causes profound and global peroxisome deficiency, and is associated with growth delay, severe hypotonia, and death shortly after birth, similar to Zellweger syndrome in humans." (PMID 40949164, 2025). "Moreover, PEX13 also displayed profuse mitochondria localization in PEX3-deficient human fibroblasts derived from Zellweger syndrome patients." (PMID 38088545, 2024). "Interestingly, mutations in PEX13 have been shown to be linked to classical Zellweger syndrome, including intra-uterine growth retardation, hypotonia, abnormal peroxisomal metabolism and neonatal lethality." (PMID 31267012, 2019). "Among these PEX13 is known to associate with Zellweger syndrome." (PMID 29416564, 2018). "Currently, several mouse models of the Zellweger spectrum disorders are available, which are represented by mice with targeted deletions in the genes encoding the peroxins PEX2, PEX5 or PEX13." (PMID 26686055, 2016). "Zellweger spectrum disorders (ZSDs), including archetypal Zellweger syndrome, neonatal adrenoleukodystrophy (NALD) and infantile Refsum disease (IRD), are PBDs caused by mutations in peroxin genes (PEX1, PEX2, PEX3, PEX5, PEX6, PEX10, PEX11β, PEX12, PEX13, PEX14, PEX16, PEX19 or PEX26)." (PMID 40949164, 2025). "A PEX13 sequence based mutation on the non-deleted chromosome could conceivably give rise to a clinical phenotype that differs from Zellweger syndrome and sequencing of this gene is considered." (PMID 29416564, 2018). "Mutant Pex13 mouse pups, exhibiting the Zellweger syndrome, lacked morphologically intact peroxisomes, displayed defective peroxisome biogenesis and showed deficient import of matrix proteins." (PMID 31267012, 2019).
peroxisomal biogenesis disorder (2 papers, 2017 to 2025). "Of note, three of the four PEX proteins (PEX2, PEX7 and PEX13 targeted by HIV-induced miRNAs are associated with peroxisome biogenesis disorders." (PMID 28594894, 2017). "In contrast to other peroxisomal biogenesis disorder (PBD) mouse models (such as the Pex5, Pex2, Pex13 knockout mice), which mimic the Zellweger spectrum symptoms, the Pex11a knockout mice still contain peroxisomes that harbor the typical peroxisomal marker enzymes." (PMID 41511296, 2025). "In cells from patients with peroxisome biogenesis disorders, peroxisomes are absent due to mutations in one or more genes that encode critical biogenesis factors including PEX2, PEX7 and PEX13." (PMID 28594894, 2017).
AIDS (1 paper, 2017). A syndrome resulting from the acquired deficiency of cellular immunity caused by the human immunodeficiency virus (HIV). "Immunolabeling of frontal lobe sections showed that the intensity of PEX13 and thiolase immunostaining which was concentrated in astrocytes (arrows), was consistently lower in HIV/AIDS tissue compared to that from uninfected patients." (PMID 28594894, 2017).
HIV-1 infection (1 paper, 2020). The type species of lentivirus and the etiologic agent of acquired immunodeficiency syndrome (AIDS). "Seventy-two hours later, the relative levels of four peroxisomal biogenesis factors (PEX2, PEX7, PEX11B, and PEX13) that are downregulated during HIV-1 infection of human cells were assessed by immunoblotting." (PMID 32127461, 2020).
Hyperoxaluria (1 paper, 2024). Increased excretion of oxalates in the urine. "It has been associated with hyperoxaluria with NL and NC with variants in PEX1, likely with variants in PEX5, and possibly with variants in PEX3, PEX6, PEX 10, PEX 12, PEX13, PEX14, PEX16, PEX19, and PEX26." (PMID 38606357, 2024). "It has been associated with hyperoxaluria with NL and NC with variants in PEX1 and PEX3, likely with variants in PEX5, and possibly with variants in PEX6, PEX7, PEX10, PEX11, PEX12, PEX13, PEX16, and PEX26." (PMID 38606357, 2024).
Obesity (1 paper, 2022). Accumulation of substantial excess body fat. "Abcg1, Aldoa, Mrap, Pex13, Aldh6a1, Egln3, G0s2 and Syn2 are significantly increased in adipose or liver tissue of ob/ob mice compared with lean mice, suggesting these genes are associated with obesity, are very rarely reported to be related to adipogenesis." (PMID 34974794, 2022).
Parkinson disease (1 paper, 2024). A progressive degenerative disorder of the central nervous system characterized by loss of dopamine producing neurons in the substantia nigra and the presence of Lewy bodies in the substantia nigra and locus coeruleus. "One such substrate is αS, the protein commonly known for its oligomerization and deposition within pathological inclusions in Parkinson’s Disease, that has been shown to oligomerize in several ZSD models including PEX13 deficient mice." (PMID 38195640, 2024).
virus infection (1 paper, 2017). "Strikingly, Bcl-xL-TM, VAMP-2-TM or Pex13-TM could not inhibit MAVS activity in inducing IFN production following virus infection, nor was MAVS aggregation affected." (PMID 28607490, 2017).
infection (6 papers, 2017 to 2022). The state of being infected such as from the introduction of a foreign agent such as serum, vaccine, antigenic substance or organism. "The upregulation of PEX5 and PEX13 was observed under ScYLV infection and a heat map was drawn as well in this experiment." (PMID 35774818, 2022). "The loss of multiple PEX proteins was evident at 24-h post-infection; however, by 48-h, the reduction in PEX3, PEX7, PEX11B, PEX13 and PEX19 was much more pronounced." (PMID 31311201, 2019). "Immunoblotting revealed that infection of primary macrophages, a physiologically relevant cell type in HIV patients, resulted in dramatic loss of PEX2, PEX7, PEX13, and to a lesser extent, PEX11B." (PMID 28594894, 2017). "In our study, two genes peroxin 2 (PEX2) and peroxin 13 (PEX13) were significantly down-regulated, which might affect peroxisomal protein import and thus fail to detoxify ROS at the infection site." (PMID 34072279, 2021). "Infection with an isogenic Nef knockout virus had a similar effect on PEX2, PEX7, PEX13, and PEX11B as wild-type HIV-1." (PMID 32127461, 2020). "Unlike wild-type HIV-1, infection with Vpu-S52,56D and Vpu-S52,56N viruses did not result in a significant loss of PEX2, PEX7, PEX11B, or PEX13 in HeLa-CD4/CXCR4/CCR5 cells, macrophages, or T cells." (PMID 32127461, 2020).
tumor (3 papers, 2021 to 2025). "In mechanistic terms, tegaserod maleate reduces proteins levels of the peroxisome membrane proteins PEX11B and PEX13, affecting the function of peroxisomes and achieving tumor suppression." (PMID 34422635, 2021). "We further explored the role of PEX11B and PEX13 in tumor suppression." (PMID 34422635, 2021). "Simultaneously, we detected the expression of PEX11B, PEX13 and PMP70 in tumor tissues by western blotting." (PMID 34422635, 2021).
PEX13 also shares sentences with these, for which no sentence is quoted: Zellweger spectrum disorders (2 papers); Breast Invasive Carcinoma (1); encephalitis (1); Infertility (1); ovarian carcinoma (1); Seckel syndrome (1); X-linked adrenoleukodystrophy (1).